GFPT1 (glutamine--fructose-6-phosphate transaminase 1)
Diseases named in the same sentence as GFPT1 in open-access papers (continued):
Sharing a sentence is not in itself a finding about the gene and the disease.
colorectal cancer (5 papers, 2013 to 2025). A primary or metastatic malignant neoplasm that affects the colon or rectum. "Overexpression of fatty acid synthase (FASN), a key enzyme in fatty acid synthesis, correlates with GFPT1 upregulation and enhanced colorectal cancer proliferation." (PMID 40830088, 2025). "In colorectal cancer, GFPT1 is connected to mitochondrial antiviral-signaling protein (MAVS) from early to late stages, supporting reprogrammed metabolic states seen in viral immune responses." (PMID 40830088, 2025). "It was suggested through our signal propagation analysis that MAVS responded to colorectal cancer in the early stage and then transmitted the disease signal to GFPT1 whose dysfunction further accelerated the colorectal cancer patients into late stage." (PMID 23586028, 2013). "Accordingly, it is rational to deduce the signal propagation from MAVS to GFPT1 as follows: in mitochondria, as an important innate immunity protein, MAVS may response to colorectal cancer in a very early stage." (PMID 23586028, 2013).
hepatocellular carcinoma (5 papers, 2015 to 2025). A malignant tumor that arises from hepatocytes. "For instance, the Forkhead box transcription factor FOXA2 promotes HBP-driven O-GlcNAcylation by transcriptionally activating GFPT1, consequently doxorubicin-induced apoptosis in hepatocellular carcinoma." (PMID 40830088, 2025). "High GFPT1 expression has been observed in cancer stem cells (CSCs) within pancreatic cancer and hepatocellular carcinoma stem cell-like populations." (PMID 40830088, 2025). "Hep3B2.1-7 cells, a human hepatocellular carcinoma cell line, were used as a positive control for GFPT1 protein expression." (PMID 39664728, 2024).
Insulin resistance (5 papers, 2013 to 2025). Increased resistance towards insulin, that is, diminished effectiveness of insulin in reducing blood glucose levels. "GFPT1 is the key enzyme in hexosamine synthesis pathway whose products have been implicated in O-linked N-acetylglucosamine (O-GlcNAc) protein modification, insulin resistance, and glucose toxicity." (PMID 23586028, 2013).
liver cancer (4 papers, 2022 to 2025). An epithelial or non-epithelial malignant neoplasm that arises from the liver. "Importantly, clinical datasets further supported the correlations between GFPT1/ANGPTL4 expression and cholesterol levels in Non-Alcoholic Steatohepatitis (NASH) liver cancer patients." (PMID 40806239, 2025).
gastric cancer (3 papers, 2016 to 2025). A primary or metastatic malignant neoplasm involving the stomach. "In gastric cancer, recent studies show that high GFPT2 expression correlates with increased tumor invasion and poor patient outcomes, while downregulation of GFPT1 in the same cancer type is similarly associated with EMT, invasion, and adverse prognosis." (PMID 40830088, 2025). "Similar predictive value of GFPT1 for overall survival in both subgroups was also observed in the gastric cancer patients from the TCGA dataset." (PMID 27509259, 2016). "Together, these results suggest that GFPT1 functions as a suppressor of epithelial-to-mesenchymal transition in gastric cancer cells." (PMID 27509259, 2016). "Though HBP has been considered to link glucose metabolism to malignant transformation, the expression and biological function of GFPT1 in gastric carcinoma remains little investigated." (PMID 27509259, 2016). "Given the established links between GFPT isoforms and tumor progression, the contrasting roles of GFPT1 and GFPT2 in gastric cancer warrant further investigation." (PMID 40830088, 2025).
glioblastoma (3 papers, 2020 to 2025). The most malignant astrocytic tumor (WHO grade IV). "In glioblastoma, c-Myc-dependent activation of GFPT1 is linked to cancer cell proliferation, invasion, and metastasis." (PMID 40830088, 2025). "In glioblastoma, GFPT1 and mTORC2 form a regulatory network that adapts cancer metabolism to cellular nutrient levels." (PMID 40830088, 2025). "In contrast, GFPT1 expression was lower in GBM (glioblastoma multiforme, p = 0.020), KIRC (kidney renal clear cell carcinoma, p = 3.79E-06), KIRP (kidney renal papillary cell carcinoma, p = 0.016), and THCA (thyroid carcinoma, p = 7.99E-05) tumor tissues compared to normal tissues." (PMID 39664728, 2024).
myasthenia (3 papers, 2016 to 2023). "As CMS patients with loss-of-function variants in GFPT1 demonstrate a limb-girdle pattern of myasthenia, we analyzed motor functions and the NMJ structures in KO mice." (PMID 37744035, 2023).
prostate carcinoma (3 papers, 2013 to 2023). A carcinoma that arises from epithelial cells of the prostate gland. "We found that two enzymes of the HBP, namely GFPT1 and UAP1 are up-regulated in prostate cancer cell lines." (PMID 23724116, 2013). "Interestingly, the expression of both GFPT1 and UAP1 was increased by ∼50% in AR-positive prostate cancer cell lines LNCaP and VCaP compared to normal prostate cells PNT2 and RWPE-1." (PMID 23724116, 2013).
colon adenocarcinoma (2 papers, 2017 to 2024). "Furthermore, our data on regulation of metastasis by GFPT1 is supported by studies showing a tight link between the HBP/GFPT1 and EMT and a study demonstrating that the downregulation of GFPT1 inhibits cell motility and metastasis in a mouse model of CRC murine colon adenocarcinoma cells." (PMID 38732103, 2024).
esophageal cancer (2 papers, 2022). A primary or metastatic malignant neoplasm involving the esophagus. "ELFN1-AS1 promoted tumor cell proliferation and metastasis by acting as a sponge of miR-183-3p to upregulate GFPT1 in esophageal cancer." (PMID 35494024, 2022).
muscle disorder (2 papers, 2015 to 2022). "The findings of our study further expanded the phenotypic spectrum of GFPT1-related LG-CMS and improved our understanding of this rare muscle disorder in clinical practice." (PMID 36188410, 2022).
myasthenia gravis (2 papers, 2022). Myasthenia gravis (MG) is a rare, clinically heterogeneous, autoimmune disorder of the neuromuscular junction characterized by fatigable weakness of voluntary muscles. "Accordingly, clinical physicians should carefully make differential diagnosis between the GFPT1‐related CMS and myasthenia gravis, metabolic myopathies, or limb‐girdle muscle dystrophy." (PMID 34978387, 2022). "Therefore, like myasthenia gravis, whether there was a correlation between high-frequency RNS and the severity of clinical symptoms in patients with GFPT1-related LG-CMS deserves a further study of high-frequency RNS in a larger sample of CMS patients with GFPT1 mutations from different countries." (PMID 36188410, 2022).
myofibrillar myopathy (2 papers, 2022 to 2023). "It was puzzling that GFPT1 defect in patient one was associated with atypical pathological changes of myofibrillar myopathy (MFM) characterized by desmin deposits, Z‐disc disorganization, and electronic dense granulofilamentous aggregation." (PMID 34978387, 2022). "Three patients with GFPT1-CMS had rimmed vacuoles in skeletal muscle, and 2 patients with GFPT1-CMS had myofibrillar myopathy with deposition of desmin." (PMID 36835142, 2023).
vacuolar myopathy (2 papers, 2022 to 2025). "In this study, we described two CMS patients with GFPT1 mutations: one presented with vacuolar myopathy with myofibrillar destruction, and the other showed typical myopathy with tubular aggregates." (PMID 34978387, 2022). "In summary, besides the common tubular aggregates, the muscle pathological changes of GFPT1‐related CMS also can show rimmed vacuolar myopathy, autophagic vacuolar myopathy, mitochondria‐like myopathy, MFM‐like myopathy, neurogenic features, and unspecific myopathy changes." (PMID 34978387, 2022). "Among the 51 reported GFPT1‐related CMS patients with muscle biopsy, most of them showed tubular aggregates myopathy, while rimmed vacuolar myopathy, autophagic vacuolar myopathy, mitochondria‐like myopathy, neurogenic myopathy, and unspecific myopathic changes were also observed in some patients." (PMID 34978387, 2022).
acute myeloid leukemia (1 paper, 2025). Acute myeloid leukemia (AML) is a group of neoplasms arising from precursor cells committed to the myeloid cell-line differentiation. "Intriguingly, GFPT1-driven O-GlcNAcylation also modulates AKT activation, as lower O-GlcNAcylation levels, induced by pharmacological inhibition of GFPT1 or OGT, correlate with heightened AKT phosphorylation at Ser473 and Thr308 in acute myeloid leukemia (AML) cells." (PMID 40830088, 2025).
adenoma (1 paper, 2024). A neoplasm arising from the epithelium. "Immunohistochemistry analysis demonstrates that FASN, GFPT1 and OGT are highly expressed in mouse Apc/Cre intestinal adenomas as compared to surrounding normal mucosa and the patterns of FASN and GFPT1 expression are very similar in adenoma tissues." (PMID 38732103, 2024). "In summary, our data suggest that upregulation of FASN during Apc-driven carcinogenesis increases the expression of GFPT1 and OGT and the level of O-linked glycosylation of proteins in intestinal and adenoma tissues." (PMID 38732103, 2024). "Western blot analysis on adenoma tissues confirmed that downregulation of FASN leads to a decrease in GFPT1 and OGT protein expression, with a more profound effect on expression of GFPT1." (PMID 38732103, 2024). "In summary, we show that an increase in FASN expression during adenoma formation and CRC progression leads to the upregulation of GFPT1 and OGT, as well as an increase in the level of O-GlcNAcylation and, consequently, to enhanced cellular proliferation, tumor growth and metastasis." (PMID 38732103, 2024).
autism spectrum disorder (1 paper, 2024). A spectrum of developmental disorders that includes autism, and Asperger syndrome. "In rare cases, the GFPT1 mutation is associated with a certain level of cognitive impairment that ranges from mild learning difficulties to autism spectrum disorder." (PMID 39559672, 2024).
cataract (1 paper, 2022). Partial or complete opacity of the crystalline lens of one or both eyes that decreases visual acuity and eventually results in blindness. "In our study, one of the younger sisters of patient 1, with the same homogenous GFPT1 missense mutations as patient 1, presented with congenital cataracts and prominent fluctuating and fatigable limb weakness." (PMID 36188410, 2022). "Therefore, we suggest that cataracts may be a genetically distinct disease entity that are independent of GFPT1-related CMS in this family." (PMID 36188410, 2022).
congenital muscular dystrophy (1 paper, 2024). A muscular dystrophy that is characterized by diminished muscle tone (hypotonia), progressive muscle weakness and degeneration (atrophy), abnormally fixed joints, spinal rigidity, and delays in reaching motor milestones such as sitting or standing unassisted. "Causative variants were found in nine patients with congenital muscular dystrophy in the ACTA1 gene (in one patient), GFPT1 (in one patient), PIGY (in two patients), POMT1 (in one patient), MCU1 (one patient), RYR1 (one patient), and TTN (one patient)." (PMID 37989827, 2024).
epilepsy (1 paper, 2025). A brain disorder characterized by episodes of abnormally increased neuronal discharge resulting in transient episodes of sensory or motor neurological dysfunction, or psychic dysfunction. "To our knowledge, we present the first patient with epilepsy associated with GFPT1-CMS, possibly expanding the neurological spectrum of the disease." (PMID 41323224, 2025). "Nevertheless, this case series possibly expands the known phenotypic spectrum of GFPT1-CMS, notably reporting the first association with epilepsy, and demonstrates the utility of muscle ultrasound in characterizing structural muscle changes in these patients." (PMID 41323224, 2025). "Moreover, the identification of cognitive compromise and epilepsy in one patient suggests that GFPT1-related disease may, in rare cases, extend beyond the neuromuscular junction." (PMID 41323224, 2025). "We conclude that GFPT1-CMS may present with variable severity of proximal and distal muscle weakness and, in some cases, be accompanied by additional features such as intellectual developmental disorder and epilepsy." (PMID 41323224, 2025). "Patient 5 showed additional features not typically described in GFPT1-CMS, including intellectual disability, psychiatric symptoms, and epilepsy." (PMID 41323224, 2025).
glycosylation disorders (1 paper, 2019). "However, in glycosylation disorders due to mutations in the GFPT1 gene tubular aggregates with synaptopathy and dramatic loss of post-synaptic functional folds and evidence of denervations/reinnervation processes affecting the three main NMJ components can be found." (PMID 30808424, 2019).
hip osteoarthritis (1 paper, 2025). "We find that GFPT1, linked with clock entrainment, demonstrates allelic imbalance in subchondral bone; and that the hip osteoarthritis risk allele of rs6546511 is associated with increased GFPT1 expression." (PMID 40205036, 2025).
Hyperammonemia (1 paper, 2022). An increased concentration of ammonia in the blood. "The livers of mice with acute hyperammonemia showed increased concentrations of glutamine, uridine and UDP-GlcNAc, while both protein amount and catalytic activity of glutamine-fructose-6-phosphate aminotransferase 1 (GFPT1), the rate-limiting enzyme in HBP, were unaffected." (PMID 36064721, 2022).
Hyperinsulinemia (1 paper, 2020). An increased concentration of insulin in the blood. "Likewise, the GFPT1 gene is associated with familial hyperinsulinemia and acts as a negative regulator of glycogen synthesis." (PMID 32751097, 2020).
invasive breast carcinoma (1 paper, 2024). A carcinoma that infiltrates the breast parenchyma. "Additionally, GFPT1 was found to correlate with M2 macrophage infiltration and predict chemotherapy response in invasive breast cancer." (PMID 39664728, 2024). "However, the prognostic significance of GFPT1 in invasive breast cancer and its relationship with immune cell infiltration, genetic alterations, and drug sensitivity have not been thoroughly investigated." (PMID 39664728, 2024). "Glutamine-fructose-6-phosphate transaminase 1 (GFPT1) is the key regulatory enzyme in the HBP; however, its role in invasive breast carcinoma remains underexplored." (PMID 39664728, 2024).
juvenile macular degeneration (1 paper, 2022). "Retinal involvement as an additional feature has been reported in three patients with GFPT1 from two families: two having juvenile macular degeneration, and another having retinitis pigmentosa." (PMID 36188410, 2022).
medullary thyroid cancer (1 paper, 2017). "ALK fusions have also been descried in medullary thyroid cancer (EML4-ALK and Glutamine:fructose-6-phosphate transaminase 1 (GFPT1)-ALK), with patient response to crizotinib reported in an EML4-ALK patient." (PMID 28030793, 2017).
medulloblastoma (1 paper, 2022). A malignant, invasive embryonal neoplasm arising from the cerebellum. "Specifically, compared to pediatric low-grade glioma, we detected in medulloblastoma increased GFPT1, which encodes for the enzyme GFAT that converts fructose-6P to glucosamine-6P, the rate-limiting step in hexosamine synthesis." (PMID 35267619, 2022).
pancreatic adenocarcinoma (1 paper, 2024). "In contrast, pancreatic adenocarcinoma tissues showed lower GFPT1 protein expression compared to normal tissues." (PMID 39664728, 2024).
ptosis (1 paper, 2022). The drooping of the upper eyelid. "Most of these CMS are accompanied by additional features such as dysmorphism (CHRNA1), or limb-girdle pattern of weakness (GFPT1; GMPPB; DGPAGT1) without EOM weakness or ptosis." (PMID 35280301, 2022).
renal carcinoma (1 paper, 2014). A carcinoma arising from the epithelium of the renal parenchyma or the renal pelvis. "By contrast, in renal carcinoma cells that do not produce N-GlcNAc2-modified proteins, GFPT1 and UAP1 were less activated (i.e.,<2-fold increase) by glucose deprivation over the same timescale." (PMID 24796485, 2014).
Respiratory insufficiency (1 paper, 2024). "The patient had respiratory insufficiency, which is not commonly seen in the GFPT1 mutation; it is usually associated with mutations of RAPSYN, COLQ, MUSK, and others." (PMID 39559672, 2024).
retinal disease (1 paper, 2022). "Whether the retinal disease is associated with GFPT1 mutations, or a genetically distinct disorder is unclear." (PMID 36188410, 2022).
scoliosis (1 paper, 2024). A congenital or acquired spinal deformity characterized by lateral curvature of the spine. "It is important to note that scoliosis is not generally linked to the GFPT1 mutation, and based on our case, it contributed to a broader and more complex clinical presentation." (PMID 39559672, 2024). "Finally, scoliosis itself is typically associated with mutations of the COLQ, VAMP1, and CHRNE (slow channel syndrome) genes rather than GFPT1 mutations." (PMID 39559672, 2024).